TNF (tumor necrosis factor)
Diseases named in the same sentence as TNF in open-access papers (continued):
Sharing a sentence is not in itself a finding about the gene and the disease.
renovascular hypertension (5 papers, 2018 to 2024). High blood pressure secondary to renal artery stenosis. "In cardiac inflammation caused by renovascular hypertension, CA may interact with TNF α, IL-17, COX2, and MMP9 to affect their protein stability and reduce their expressions, thus playing a role in improving inflammation." (PMID 39337549, 2024). "In the present study, we observed that renovascular hypertension increased the concentrations of IL-1β, IL-6, and TNF-α in the duodenum of 2K1C rats." (PMID 34777003, 2021). "Renovascular hypertension indicated an inflammatory process in the gastrointestinal tract, with increased levels of IL-1β and IL-6 and TNF-α in the duodenum." (PMID 34777003, 2021). "Continuous infusion of pentoxifylline, a TNF-α inhibitor, into the lateral ventricle of the brain for 14 consecutive days reduced blood pressure and improved baroreflex sensitivity in renovascular hypertensive rats." (PMID 31114507, 2019). "Our findings provide evidence that the central inhibition of TNF-α reduces arterial pressure in renovascular hypertensive rats." (PMID 31114507, 2019). "In conclusion, central inhibition of TNF-α reduces arterial pressure in renovascular hypertensive rats." (PMID 31114507, 2019). "In this study, we showed that AngII-induced renovascular hypertension up-regulated TNF and CX3CL1 production in T. cruzi-infected rats, thereby further potentiating cardiac inflammation and fibrosis." (PMID 29590257, 2018). "In addition, central inhibition of TNF-α reduced the increased power of the LF band of SAP spectrum in animals with renovascular hypertension, corroborating the ganglionic blocker studies." (PMID 31114507, 2019). "Our findings suggest that TNF-α play an important role in the maintenance of sympathetic vasomotor tone and increased oxidative stress in the RVLM during renovascular hypertension." (PMID 31114507, 2019). "The aim of this study was to evaluate systemic AngII, tumor necrosis factor (TNF), and CX3CL1 mediators in a two-kidney one-clip (2K1C) renovascular hypertension model using Wistar rats infected with T. cruzi." (PMID 29590257, 2018). "Chronic inhibition of the angiotensin-converting enzyme in the paraventricular nucleus of the hypothalamus (PVN) attenuates both sympathoexcitation and ROS accumulation, and modulates expression of cytokines (decreasing TNF-α, IL-1β, and IL-6) in the RVLM during renovascular hypertension." (PMID 31114507, 2019). "Using combined in vivo and in vitro approaches, we investigated the effects of central inhibition of TNF-α on blood pressure, sympathetic tone, baroreflex sensitivity, and oxidative stress in the rostral ventrolateral medulla (RVLM) of rats with 2-kidney-1-clip (2K1C) renovascular hypertension." (PMID 31114507, 2019). "However, direct central inhibition of pro-inflammatory mediators, such as TNF-α, on sympathetic activity, baroreflex sensitivity and ROS accumulation in the RVLM of renovascular hypertensive rats has not been investigated." (PMID 31114507, 2019).
retinoblastoma (5 papers, 2017 to 2022). A malignant tumor that originates in the nuclear layer of the retina. "Apart from cell cycle-associated genes, inflammatory pathways including Wnt, TNF, T cell receptor and B cell receptor are also found to be modulated in Rb tumors." (PMID 35359459, 2022). "For TNF gene amplification analysis, 30% (3/10) retinoblastoma tumour samples harboured more than two copies of TNF gene." (PMID 28575107, 2017). "Besides, our results suggested H3K27ac modification due to metformin treatment was involved in retinoblastoma gene in cancer, G1/S specific transcription, interleukins and inflammatory response, TNF signaling pathway, programmed cell death and BMP signaling pathway." (PMID 35399730, 2022). "In our study, the oncogenic inflammatory pathways including Wnt, TNF, T cell receptor identified by PANTHER and ShinyGO v0.61 analysis in Rb tumors are reported to induce apoptosis in Rb tumor cells." (PMID 35359459, 2022). "FASLG, TNF, TNFRSF9, and TNFRSF1A, genes involved in FAS and TNF pathways, were expressed at significantly higher levels in Y79 retinoblastoma cells treated with magnetic hyperthermia compared to untreated cells." (PMID 31602343, 2019).
retinopathy of prematurity (5 papers, 2013 to 2021). A bilateral retinopathy characterized by neovascularization, scarring, retinal detachment, and eventually blindness. "A recent study by Connor et. al. which used the rodent model of retinopathy of prematurity demonstrated that increasing n-3 PUFAs levels by either dietary or genetic means decreased retinal TNFα levels and lessened microvessel pathology." (PMID 23383097, 2013). "In parallel, the levels of multiple proinflammatory cytokines, including TNF-α and IL1- β, are increased in the vitreous of patients with PDR and retinopathy of prematurity, further supporting the importance of inflammation in driving ischemia-induced NV." (PMID 34673570, 2021).
seminoma (5 papers, 2023 to 2025). A radiosensitive malignant germ cell tumor found in the testis (especially undescended), and extragonadal sites (anterior mediastinum and pineal gland). "Taken together, we unveiled the functionally discrete roles of IL-6 and TNFα in shaping the pro-inflammatory TME in seminomas, although we cannot exclude the possibility that tumor cells produce additional soluble factors like the chemokines CXCL10 that are involved in this process." (PMID 40649953, 2025). "In agreement with this hypothesis, an overexpression of IL-1β, IL-6 and TNF-α has been reported in seminoma." (PMID 37371875, 2023). "Furthermore, as we previously published, seminomas revealed high IFNG and TNF expression, while the expression of these genes were low in NSGCT." (PMID 40011822, 2025). "Using TCGA mRNA expression of anabolic (CYP2R1, CYP27A1 and CYP27B1) and catabolic (CYP24A1) Vitamin D enzymes, positive (PTHLH, IFNG, and TNF) and negative (FGF23) feedback regulators could also clearly distinguish between pure seminomas and NSGCT." (PMID 37242266, 2023).
Skin ulcer (5 papers, 2022 to 2025). A discontinuity of the skin exhibiting complete loss of the epidermis and often portions of the dermis and even subcutaneous fat. "The presentation of medium-vessel vasculitis in the context of TNF inhibitors often includes different patterns of erythematous rash, skin ulcers, or nodules." (PMID 41158918, 2025). "Relevant studies have reported that Panax Notoginseng Saponins (PNS) can alleviate skin ulcers in diabetic rats by reducing the expression of endothelin-1 (ET-1) and tumor necrosis factor-α (TNF-α)." (PMID 35069970, 2022). "Compared with the Mod group, the contents of TNF-α in the skin ulcer tissue of the rats with SK or Mup treatment were significantly lower (P < 0.05)." (PMID 35222679, 2022). "The experiment showed that the level of TNF-α in the skin ulcer tissue of rats in the administration groups both decreased." (PMID 35222679, 2022).
Stevens-Johnson syndrome (5 papers, 2021 to 2024). Stevens-Johnson syndrome is a limited form of toxic epidermal necrolysis characterized by destruction and detachment of the skin epithelium and mucous membranes involving less than 10% of the body surface area. "Erythema multiforme and Stevens-Johnson syndrome can also be triggered by viral infections such as herpes or other drugs which should also be considered as the underlying cause in patients with IBD receiving TNF-blockers." (PMID 33802483, 2021). "Stopping anti-TNF-α therapy should be considered in case of severe Stevens-Johnson syndrome and TEN." (PMID 33802483, 2021).
Stillbirth (5 papers, 2012 to 2024). Death of the fetus in utero after at least 22 weeks of gestation. "There was also a significant increase in WBCs, Hb, RBc count, birth weight and body temperature with significantly decreased in the serum levels of TNF-α and stillbirth of newly born lambs from supplemented ewes as compared to other lambs from control ones." (PMID 38702499, 2024). "The current study found that supplementing late-pregnant Barki ewes with nannochloropsis at the late stage of pregnancy raised the body temperature and birth weight of the lambs, while lowering the percentage of stillbirths and blood levels of TNF-α." (PMID 38702499, 2024). "The congruence between elevated MCP-1 and TNF-α in amniotic fluid of CMV-infected pregnant women and tissue fixed cytokine in both CMV-infected stillbirth placentae and ex vivo placental explant histocultures suggests the amniotic fluid cytokine changes are related to placental changes." (PMID 23300810, 2012). "For example, high levels of MIF (along with other factors such as TNF) can activate the inducible cyclooxygenase (COX)-2 pathway, leading to higher prostaglandin production and potentially other pathways that contribute to stillbirth and LBW." (PMID 23272137, 2012). "Expression of MCP-1 and TNF-α is elevated in CMV-infected placentas from stillbirths: MCP-1 and TNF-α protein localized in syncytiotrophoblasts, cytotrophoblasts, mesenchymal, and endothelial cells of chorionic villi in CMV-infected placentas and uninfected placentas from stillbirths." (PMID 33374185, 2020).
synucleinopathies (5 papers, 2017 to 2025). "TNFα-dependent neuroinflammation may play a key role in MSA pathogenesis, and its relevance has been underlined in various models of synucleinopathy." (PMID 30975183, 2019). "Both IFN-γ and TNFα have been shown to be associated with neurodegeneration in PD mouse models while the role of other cytokines, such as IL-6 and IL-4 that are upregulated in PD patients, have not been studied before in mouse models of synucleinopathies." (PMID 28049533, 2017).
tongue cancer (5 papers, 2017 to 2025). A malignant neoplasm affecting the tongue. "In mouse models with tongue cancer, the addition of Lactobacillus fermentum increased the levels of G-CSF, GM-CSF, IgG, IgM, IL-4, IL-12, TNF-alpha, and IFN-gamma." (PMID 41155504, 2025). "TPL suppressed the expression of cytokines IL-6, IL-8, and TNF-α, as well as tumor growth, invasion, migration, and angiogenesis in the co-inoculation of human tongue cancer cells with macrophage-like U937 cells." (PMID 27073100, 2017). "TPL suppressed the expression of cytokines IL-6, IL-8, and TNF-α and repressed tumor growth, invasion, migration, and angiogenesis in co-inoculation of human tongue cancer cells with macrophage-like U937 cells." (PMID 27073100, 2017). "In this study, LF-CQPC08 increased the serum levels of IL-4, IL-12, TNF-α, and IFN-γ in mice with induced tongue cancer, thereby regulating the immune system and inhibiting the tongue cancer in the mouse model." (PMID 30861992, 2019). "The serum IL-4, IL-12, TNF-α, and IFN-γ levels of the mice in the normal group were the highest, while the results in the mice with induced tongue cancer in the control group were the opposite." (PMID 30861992, 2019).
tongue squamous cell carcinoma (5 papers, 2015 to 2022). A squamous cell carcinoma that arises from the tongue. "In one study, salivary levels of IL-1α, IL-6, IL-8, vascular endothelial growth factor A (VEGF-a) and TNF-α were able to predict the progression of tongue SCC from high-risk to neoplasm, serving as potential biomarkers for cancer screening and early detection." (PMID 26082902, 2015). "But the percentages of CD8+IFN-γ+ and CD8+IFN-γ+ TNF-α+ T cells were significantly lower in grade II + III in comparison with grade I of the tongue SCC (P = 0.035 and P = 0.043, respectively)." (PMID 36376825, 2022). "In addition, the frequency of CD4+IFN-γ+TNF-α+ T cells showed a non-significant increasing trend in TDLNs of laryngeal compared with tongue SCC (P = 0.086)." (PMID 36376825, 2022).
tuberculoid leprosy (5 papers, 2011 to 2023). A principal or polar form of leprosy in which the skin lesions are few and are sharply demarcated. "This supports previous studies which found that the xenophagy inhibiting IL-10 cytokine is predominant in multibacillary leprosy (MB) compared to high levels of IL-26, IFN-γ, and TNF-α (xenophagy-inducing cytokines) found during paucibacillary tuberculoid leprosy (PB)." (PMID 38133338, 2023). "Of the 24 soluble mediators of inflammation that were measured, 7 showed significant differences between lepromatous and tuberculoid leprosy (CCL2, CCL17, CCL18, IFNA1, IL10, IL22, and TNF)." (PMID 25412496, 2014).
unstable angina pectoris (5 papers, 2020 to 2023). "The deviation from Hardy–Weinberg equilibrium (HWE) of TNF-alpha genotypes was obvious in control and unstable angina pectoris groups." (PMID 36622512, 2023). "The levels of TNF-alpha were significantly higher in patients with stable and unstable angina pectoris in comparison with controls." (PMID 36622512, 2023).
valvular heart disease (5 papers, 2017 to 2025). "TNF-α was associated with the pathogenesis of chronic AF, and increased levels of TNF-α and atrial fibrosis were often detected in AF patients with valvular heart disease." (PMID 37396579, 2023). "The modified valves exhibited tumor necrosis factor (TNF)-α reduction and interleukin (IL)-10 enhancement results revealed superb applicability for valvular heart disease." (PMID 36144581, 2022).
viral meningitis (5 papers, 2012 to 2024). Inflammation of the membranes surrounding the brain and spinal cord due to a viral infection. "Previous studies have found increased levels of inflammatory cytokines and chemokines in the CSF of patients with viral meningitis, such as IL‐6, IL‐1b, TNF‐α, IL‐10, CXC family chemokines and growth factors." (PMID 37904697, 2023). "There are some inflammatory mediators in CSF or serum that help to differential diagnosis of bacterial and viral meningitis such as IL6, CRP, Pre- calcitonin, TNF, IL8." (PMID 23483792, 2012).
vulvovaginal candidiasis (5 papers, 2018 to 2024). Infection of the vulva and vagina with a fungus of the genus CANDIDA. "The same trend was also evident in the vaginal candidiasis-associated inflammatory cytokines, IL-17, IL-22, and TNF-α." (PMID 31333606, 2019). "In addition, oral administration of HY7801 improves vulvovaginal candidiasis by inhibiting the survival of Candida albicans and down-regulating TNF-α, COX-2, iNOS, and IL-1β levels." (PMID 32384794, 2020).
Acidosis (4 papers, 2018 to 2025). Abnormal acid accumulation or depletion of base. "Acidosis markedly suppresses several cytokines central to control of M.tb infection including TNF-α and IFN-γ." (PMID 37418488, 2023). "Acidosis markedly suppressed TNF-α secretion by infected MDMs despite increases in TNF expression." (PMID 37418488, 2023). "Inflammation: Acidosis led to an increase in COX-2 in NRK-52E and TNF in NRK-49F in monoculture." (PMID 35327483, 2022).
acute cholangitis (4 papers, 2016 to 2024). Cholangitis that is both sudden in onset and of a relatively short duration. "The injured biliary epithelial cells then secrete proinflammatory and chemotactic cytokines, such as TNF-α and IL-6, causing acute cholangitis, ductular reaction and finally biliary fibrosis." (PMID 26967735, 2016). "Pre-transplant data also indicates a sevenfold heightened risk of developing acute cholangitis with anti-TNFα agents (compared to no anti-TNFα treatment)." (PMID 37841645, 2023).
Acute encephalopathy (4 papers, 2018 to 2020). "Some studies have shown that serum IL-6, IL-10, and TNF-α levels were elevated in KD, and these cytokines could cause brain damage in acute encephalopathy following prolonged febrile seizures." (PMID 31922014, 2018). "Here, we retrospectively investigated levels of serum PCT, C-reactive protein (CRP), and inflammatory cytokines (IL-6, TNF-α, and IFN-γ) in the second phase of patients with acute encephalopathy with biphasic seizures and late reduced diffusion (AESD)." (PMID 29725488, 2018).
adrenocortical carcinoma (4 papers, 2010 to 2023). "With respect to adrenal autoimmunity, TLR3-expressing adrenocortical carcinoma cells stimulated with poly(I:C) along with IFN-γ or tumor necrosis factor α display significant rise in production of CXCL10, a chemokine involved in autoimmune adrenal failure." (PMID 26318769, 2016).
aggressive periodontitis (4 papers, 2015 to 2022). "Association between tumor necrosis factor-α (TNF-α) G-308A (rs1800629) polymorphism and susceptibility to aggressive periodontitis (AgP) were inconsistent, hence we performed this meta-analysis to clarify the association between them using Comprehensive Meta-Analysis v2.2 software." (PMID 26750615, 2016). "In studies of aggressive periodontitis (PDag) and chronic PD (CPD), 6 proinflammatory mediators (IL-1β, IL-6, IFN-γ, TNF-α, IL-17, and IL-12) and 2 common anti-inflammatory mediators (TGF-β and IL-4) were involved." (PMID 26339136, 2015).
aging (4 papers, 2021 to 2025). A developmental process that is a deterioration and loss of function over time. "Among these inflammation regulators, heightened TNF production was an essential part of the inflammatory microenvironment of aging diseases." (PMID 34722509, 2021). "The key cytokines involved in the pathogenesis of skin aging included interleukins such as IL-6, COL-I, TNF-α, and IL-1β." (PMID 40872627, 2025).
ameloblastoma (4 papers, 2017 to 2024). The most common odontogenic tumor, arising from the epithelial component of the embryonic tooth and usually affecting the molar-ramus region of the mandible or maxilla. "Several studies reported that some cytokines were secreted from ameloblastoma cells, including IL-1α, IL-1β, IL-6, and TNF-α." (PMID 35243014, 2022). "Other group reported that TNF‐α induced the expression IL‐6 and MMP‐9 from ameloblastoma cells." (PMID 29226086, 2017).